RAB3D (RAB3D, member RAS oncogene family)
Description:
The small GTPases Rab are key regulators of intracellular membrane trafficking, from the formation of transport vesicles to their fusion with membranes. Rabs cycle between an inactive GDP-bound form and an active GTP-bound form that is able to recruit to membranes different sets of downstream effectors directly responsible for vesicle formation, movement, tethering and fusion (By similarity). RAB3D may be involved in the insulin-induced exocytosis of GLUT4-containing vesicles in adipocytes (By similarity).
Synonyms: GOV; RAB16; D2-2; RAD3D
Tractability: Small molecule: a structure with a bound ligand is known; it has a binding pocket of medium quality. Antibody: UniProt places it where antibodies can reach, with high confidence; its Gene Ontology location is reachable by antibodies, with high confidence. PROTAC: its protein half-life has been measured.
Gene: Protein-coding gene on chromosome 19 (11,322,068 to 11,346,270, reverse strand). Ensembl gene ENSG00000105514.
Subcellular location: Cell membrane
Subcellular location (Human Protein Atlas): Vesicles
Pathways (Reactome):
Immune System: Neutrophil degranulation
Metabolism of proteins: RAB geranylgeranylation
Gene Ontology:
Molecular function: G protein activity; myosin V binding; protein binding; GTPase activity; GTP binding; GTP-dependent protein binding
Biological process: bone resorption; positive regulation of regulated secretory pathway; exocytosis; regulation of exocytosis
Cellular component: cytoplasmic microtubule; extracellular exosome; secretory vesicle; azurophil granule membrane; endosome; plasma membrane; synaptic vesicle; secretory granule; zymogen granule
Genetic constraint (gnomAD): Loss-of-function variants: 18 observed, 21.59 expected, observed/expected ratio (o/e) 0.83, 90% interval 0.57 to 1.24. The upper end of that interval is the gene's LOEUF score, 1.24, which puts it in group 5 of 6, group 1 being the genes least tolerant of losing a copy. Missense variants: 223 observed, 305.57 expected, observed/expected ratio (o/e) 0.73, 90% interval 0.65 to 0.81. Synonymous variants: 103 observed, 123.18 expected, observed/expected ratio (o/e) 0.84, 90% interval 0.71 to 0.99.
Homologues: Orthologues: chimpanzee RAB3D (99% identical), macaque RAB3D (99% identical), dog RAB3D (95% identical), mouse Rab3d (95% identical), pig RAB3D (93% identical), guinea pig RAB3D (93% identical), rat Rab3d (93% identical), rabbit RAB3D (87% identical), zebrafish rab3da (80% identical), tropical clawed frog rab3d (79% identical), zebrafish rab3db (77% identical). Paralogues in human: RAB3A (77% identical), RAB3B (76% identical), RAB3C (74% identical), RAB8A (44% identical), RAB10 (43% identical), RAB8B (43% identical), RAB13 (42% identical), RAB1A (42% identical), RAB1B (41% identical), RAB12 (39% identical), RAB27B (39% identical), RAB15 (39% identical), and 56 more.
Diseases named in the same sentence as RAB3D in open-access papers:
RAB3D is named in the same sentence as 30 diseases in open-access papers, as found by Europe PMC text mining. Sharing a sentence is not in itself a finding about the gene and the disease. The quoted sentences say what the papers report.
breast carcinoma (8 papers, 2015 to 2023). "Further, endocytic proteins of the RAB subfamily such as RAB3C and RAB3D control invasion and metastasis of colorectal and breast cancer, respectively." (PMID 36769293, 2023). "Elevated expression of RAB3C promotes in vivo migration, invasion, and metastasis of colorectal cancer while RAB3D induced breast cancer cell invasion by activating Akt/GSK-3β/Snail pathway." (PMID 36769293, 2023). "The knockdown of Rab3D significantly inhibited the migration abilities of breast cancer cells, which was confirmed to be mediated by Rab3D activations of AKT/GSK-3β/Snail signaling pathways." (PMID 35747825, 2022). "Studies using Rab3D knockdown or overexpression in breast cancer cells strongly suggest that this Rab-GTPase regulates EMT via the activation of the Akt/GSK-3β/Snail pathway." (PMID 34906074, 2021). "In the physiological context, Rab3D is highly correlated with tumour malignancies in breast cancer samples." (PMID 34401050, 2021). "In colorectal and breast cancer, Rab3D has been reported to promote metastasis through activating Akt/GSK3β/Snail pathway and inducing epithelial mesenchymal transition (EMT) process." (PMID 29423086, 2018). "The oncogenic activities of Rab3D have been reported in many human cancers, including colorectal cancer, breast cancer and pancreatic cancer." (PMID 29423086, 2018). "Next, we examined the Rab3D expression in clinical cancer patients' samples using immunohistochemistry on a breast cancer tissue microarray containing 50 specimens." (PMID 25823663, 2015). "Here, we demonstrated that Rab3D promotes breast cancer cell invasion and lung metastasis by EMT induction through the activation of the AKT/GSK-3β/Snail signaling pathway." (PMID 25823663, 2015). "We found that 72.2 % (26/36) malignant breast cancer tissues showed the positive staining, whereas the intensity of Rab3D staining in normal tissues or benign breast tumors was negative." (PMID 25823663, 2015). "RAB3D, a host of CTC-510F12.4, induces EMT in breast cancer cells." (PMID 34557494, 2021). "RAB3D, which is predominantly expressed in non-neuronal cells such as adipocytes and various exocrine glands, has recently been studied in breast cancer." (PMID 28784136, 2017).
osteosarcoma (5 papers, 2018 to 2024). A usually aggressive malignant bone-forming mesenchymal neoplasm, predominantly affecting adolescents and young adults. "Evidence has shown that the expression of RAB3D is upregulated by the ceRNA mechanism in non-small cell lung cancer, osteosarcoma, renal cell carcinoma, and melanoma, leading to tumor progression." (PMID 36335337, 2022). "Previous studies have pointed out that miR‐506‐3p inhibits cell growth of pancreatic cancer and induces cell apoptosis, and attenuates tumorigenesis of osteosarcoma cell by suppressing RAB3D expression." (PMID 32886453, 2020). "In the present study, therefore, we examined the relation between miR-506-3p and RAB3D in osteosarcoma tissues and several osteosarcoma cell lines." (PMID 29905536, 2018). "Using miR-506-3p gain- and loss-of-function approaches as well as a tumor model in nude mice, we revealed that miR-506-3p suppresses the proliferation and invasiveness of osteosarcoma cells by targeting RAB3D transcription." (PMID 29905536, 2018). "Real time PCR showed that RAB3D expression was significantly higher in osteosarcoma tissues than in adjacent normal tissues." (PMID 29905536, 2018). "Our results suggest that miR-506-3p acts as a tumor suppressor in osteosarcoma and that its downregulation leads to tumor cell proliferation and metastasis due to upregulation of RAB3D- and CDK4-mediated signaling." (PMID 29905536, 2018). "Our findings suggest miR-506-3p functions as a tumor suppressing by targeting RAB3D expression in osteosarcoma cells." (PMID 29905536, 2018). "In summary, our results suggest that miR-506-3p acts as a tumor suppressor in osteosarcoma and that its downregulation leads to tumor cell proliferation and metastasis due to upregulation of RAB3D- and CDK-mediated signaling." (PMID 29905536, 2018). "Suppression of miR-506-3p in osteosarcoma led to increased expression of RAB3D, which in turn led to increased CDK4 (cyclin-dependent kinase 4) and MMP9 (matrix metalloprotein 9) activities." (PMID 29905536, 2018). "In addition, when we transfected miR-506-3p mimics or miR-506-3p inhibitors into osteosarcoma cells, western blotting and real-time PCR showed that RAB3D expression suppressed by miR-506-3p mimics but enhanced by miR-506-3p inhibitors." (PMID 29905536, 2018). "Previously studies observed that RAB3D plays a key role in osteosarcoma." (PMID 29905536, 2018). "We also observed that RAB3D is upregulated in osteosarcoma cell lines and that there is a negative correlation between the expression levels miR-506-3p and RAB3D in osteosarcoma." (PMID 29905536, 2018). "The role of RAB3D in osteosarcoma progression has never been systematically studied." (PMID 29905536, 2018).
colorectal cancer (4 papers, 2017 to 2022). A primary or metastatic malignant neoplasm that affects the colon or rectum. "In summary, our study revealed miR-27b inhibited the growth and invasion of colorectal cancer cells by targeting Rab3D, and lower expression of miR-27b was associated with poor prognosis and was an independent predictor of patients’ survival." (PMID 29423086, 2018). "Conversely, high RAB3D expression is associated with tumor progression and is predictive of a poor prognosis in colorectal cancer." (PMID 29905536, 2018). "For example, Rab1a is upregulated in colorectal cancer, and Rab3d is overexpressed in a series of tumors including breast and lung cancer." (PMID 35910358, 2022). "Taken together, our study implied miR-27b inhibits cell growth and invasion by targeting Rab3D, and miR-27b is a potential biomarker for prognosis and therapeutic target in colorectal cancer." (PMID 29423086, 2018). "The result showed that the expression level of Rab3D was significantly increased in colorectal cancer compared with corresponding normal counterparts." (PMID 29423086, 2018). "Furthermore, in vitro experiments showed that miR-27b inhibited growth and invasion of colorectal cancer cells through targeting Rab3D." (PMID 29423086, 2018). "Finally, the animal experiment showed miR-27b plays a crucial role on colorectal cancer progression by targeting Rab3D." (PMID 29423086, 2018).
glioma (4 papers, 2020 to 2023). A benign or malignant brain and spinal cord tumor that arises from glial cells (astrocytes, oligodendrocytes, ependymal cells). "In our study, we found that RAB3D can act as an oncogene in glioma, and hsa_circ_0088732 can regulate RAB3D expression by sponging miR-661." (PMID 32154171, 2020). "In our study, we found that RAB3D was significantly upregulated in glioma, and negatively correlated with miR-661 expression." (PMID 32154171, 2020). "Results of Transwell assays showed that miR-661 suppressed glioma cell migration and invasion, while transfection of RAB3D partially rescued the migration and invasion mediated by miR-661 mimics." (PMID 32154171, 2020). "This study highlights the diagnostic and therapeutic potential of the hsa_circ_0088732/miR-661/RAB3D axis in glioma, and provides a theoretical mechanism for the development and occurrence of glioma." (PMID 32154171, 2020). "Transwell assays showed that the migration and invasion capabilities of LN229 and U87-MG glioma cells transfected with RAB3D siRNA were significantly reduced when compared to those capabilities for control cells (P < 0.05)." (PMID 32154171, 2020). "Therefore, we demonstrated that the effects of hsa_circ_0088732 on glioma cell apoptosis, migration, and invasion were partially due to miR-661 and RAB3D." (PMID 32154171, 2020). "Next, we further investigated the effects of RAB3D on glioma progression." (PMID 32154171, 2020). "We suggest that hsa_circ_0088732 suppresses apoptosis and promotes the migration and invasion of glioma cells via the miR-661/RAB3D axis, whose function may involve molecular targets useful for diagnosing and treating glioma." (PMID 32154171, 2020). "Moreover, hsa_circ_0088732 accelerated glioma progression through its effects on the miR-661/RAB3D axis." (PMID 32154171, 2020). "Therefore, we for the first time suggest that the hsa_circ_0088732/miR-661/RAB3D axis may be a signaling pathway that can be of assistance in diagnosing and treating glioma." (PMID 32154171, 2020). "The circRNA–miRNA–gene regulatory networks have largely found in previous exploration of circRNAs in glioma, such as circ_0074362/miR-1236-3p/HOXB7, circMAN2B2/miR-1205/SA00A8 and circ_0088732/miR-661/RAB3D." (PMID 34017919, 2021). "Additionally, hsa_circ_0088732 further accelerated the glioma cell migration and invasion mediated by miR-661 mimics and RAB3D, suggesting that the combined effects of hsa_circ_0088732 and RAB3D could rescue the migration and invasion mediated by miR-661 mimics (P < 0.05, P < 0.01)." (PMID 32154171, 2020). "Our qRT-PCR results showed that RAB3D expression was significantly upregulated in samples of glioma tissue when compared with samples of adjacent non-tumor tissue, and that levels of RAB3D expression were negatively correlated with those of miR-661 expression." (PMID 32154171, 2020).
pancreatic cancer (4 papers, 2017 to 2020). "A coexpression network revealed a hub comprising lncRNAs (MIR210HG, SNHG1, and LOC729970) and mRNAs (RAB3D, DDX17, and SPNS2) that presumably mediate drug resistance in pancreatic cancer." (PMID 31399552, 2019). "Testing additional patient‐derived pancreatic cancer cells reveals particular genes (ITGA1,TNFAIP2,COMMD7,RAB3D) that respond to APE1 knockdown similarly across all the cell lines." (PMID 28922540, 2017).
melanoma (3 papers, 2015 to 2022). A malignant, usually aggressive tumor composed of atypical, neoplastic melanocytes. "Studies to further characterize the mechanistic roles played by RAB3D in Xmrk-driven melanoma signaling and parallel studies to examine the potential role of RAB3D in human melanomas are clearly warranted." (PMID 34067095, 2021). "Also in melanoma cell lines, the levels of intracellular Rab3D were also aberrantly up-regulated in more malignant F10 cancer cells." (PMID 25823663, 2015).
Sjögren’s syndrome (3 papers, 2017 to 2023). "The enzymatic activity of Cathepsin S is upregulated in tears from Sjögren’s syndrome patients, as seen in Rab3d−/− and NOD mice." (PMID 30336591, 2018). "Moreover, co-localization of STX4 and RAB3D, a small GTPase, in mature secretory vesicles in the subapical region is altered from the apical to the basolateral plasma membrane in Sjögren’s syndrome patients." (PMID 30336591, 2018). "Interestingly, NOD mice, a mouse model for Sjögren’s syndrome, show decreased Rab3d expression and altered distribution of RAB3D from the subapical vesicles to the basolateral region." (PMID 30336591, 2018). "Patients with Sjögren’s syndrome show significant reduction in RAB3D expression, but not RAB8A, as well as the mislocalization of RAB3D from the apical to the basolateral region in salivary gland acinar cells and in lacrimal gland acinar cells." (PMID 30336591, 2018). "In addition, expression of several genes known to be dysregulated in Sjögren's syndrome: CTSS, MHC-II, MMP9, Rab proteins (Rab3D, Rab27A, and Rab27B), IL12α, IFN-γ, TNF-α, and aquaporin 5 (Aq5), and the cholinergic muscarinic M3 receptor (M3R) were quantitatively measured using qPCR." (PMID 28348600, 2017).
lung carcinoma (2 papers, 2015 to 2022). "And in other type of cancer cells such as lung cancer, the high expression of Rab3D was also observed." (PMID 25823663, 2015).
skin carcinoma (2 papers, 2015 to 2018). "We have reported, for the first time, that the levels of Rab3D are elevated in clinical patient samples with many tumor types including breast, prostate, lung, colon, ovary, liver and skin cancers and are highly correlated with tumor TNM staging." (PMID 25823663, 2015). "Moreover, RAB3D levels are much higher in breast, prostate, lung, colon, ovary, liver and skin carcinoma tissues than in corresponding normal tissues." (PMID 29905536, 2018).
asthenozoospermia (1 paper, 2023). "The proteins RAB10, RAB3D, RAB27A, and MLPH that showed a lower abundance level in asthenozoospermia and a higher abundance level in oligoasthenozoospermia were either Ras-related or were associated with sperm motility and capacitation." (PMID 37048090, 2023).
asthma (1 paper, 2023). "Specifically, we sought to examine causal mediation between PBMC key drivers associated with asthma (PRF1 and NKG7 in the NK cell module; CAPZA2, ATP6AP2, CTSS, and RAB3D from the interleukin module) and nasal key drivers associated with asthma (G3BP1 and INADL from the nasal TCA module)." (PMID 37730635, 2023).
basophilic leukemia (1 paper, 2007). "A previous study using RBL-2H3 cells, a rat basophilic leukemia-derived cell line commonly used as a model for mast cells implicated Rab3d in regulated exocytosis." (PMID 17587407, 2007).
bile duct cancer (1 paper, 2025). "Various RAB genes have been linked to tumors, including RAB27A, which serves as a predictive indicator for pancreatic ductal adenocarcinoma; RAB13 and RAB3D, which are elevated in pan-cancer; and RAB1A and RAB6A, which have significant functions in rectal cancer and bile duct cancer, respectively." (PMID 40177653, 2025).
chordoma (1 paper, 2025). Chordomas are rare malignant tumors arising from embryonic remnants of the notochord in axial skeleton. "To evaluate the roles of other RAB3 members in the chordoma stemness and tumorigenic functions, we found that RAB3A, RAB3C, and RAB3D regulated the proliferation of CH22 cells, whereas they did not control the expressions of stemness markers, such as TBXT, NANOG, OCT4 and SOX2." (PMID 40135815, 2025).
esophageal squamous cell carcinoma (1 paper, 2018). Esophageal squamous cell carcinoma (ESCC) is a type of esophageal carcinoma (EC) that can affect any part of the esophagus, but is usually located in the upper or middle third. "Silencing of RAB3D suppresses the proliferation and invasiveness of esophageal squamous cell carcinoma cells." (PMID 29905536, 2018).
hepatocellular carcinoma (1 paper, 2025). A malignant tumor that arises from hepatocytes. "Additionally, a recent study on hepatocellular carcinoma demonstrates that AMPK pathway activation stabilizes Rab3d mRNA, resulting in increased Rab3d expression." (PMID 40659647, 2025).
osteopetrosis (1 paper, 2020). Osteopetrosis, also known as marble bone disease, is a descriptive term that refers to a group of rare, heritable disorders of the skeleton characterized by increased bone density on radiographs. "Indeed, while mice deficient in Rab3D develop osteopetrosis with reduced osteoclast activity and irregular ruffled membranes, disruption of osteoclast bone resorption was dependent on guanine nucleotide binding (formation of GTP-bound Rab3D) and not on RAb3D prenylation status." (PMID 33081155, 2020).